IFNG (interferon gamma)
Diseases named in the same sentence as IFNG in open-access papers (continued):
Sharing a sentence is not in itself a finding about the gene and the disease.
ovarian carcinoma (243 papers, 1997 to 2026). A malignant neoplasm originating from the surface ovarian epithelium. "The upregulation of B7-H3 expression in ovarian cancer has been associated with a decreased number of IFNγ+ CD8+ T cells, enhanced tumor aggressiveness, and higher risk of metastasis." (PMID 40801642, 2025). "Tregs in ovarian cancer lesions suppress the immune response to tumor-associated antigens, which is achieved by suppressing the secretion of Interferon gamma (IFN-γ) and interleukin-2 (IL-2) by effector T cells." (PMID 39770446, 2024). "When considering the subset of patients with ovarian cancer across all dosing groups, increases in afami-cel doses were associated with progressively increasing peak cell persistence and peak IFNγ levels." (PMID 36624315, 2023). "Although the clinical activity in recurrent ovarian cancer was modest, the increased IFNγ production was associated with improved progression-free survival." (PMID 36831435, 2023). "Tregs found in ovarian cancer lesions suppress the immune response to tumor-associated antigens, which is achieved by the suppression of Interferon gamma (IFN-γ) and interleukin-2 (IL-2) secretion by the effector T cells." (PMID 36428581, 2022). "Enhanced infiltration of tumor-infiltrating lymphocytes (TILs) is associated with increased levels of cytokine IFNγ, a prognostic factor that indicates better survival for ovarian cancer patients." (PMID 28929459, 2018). "The heightened infiltration of TIL was associated with increased levels of the cytokine IFNγ, which is a prognostic factor for longer survival and has been studied in clinical trials for treating ovarian carcinoma." (PMID 28275576, 2017). "It was found that interferon-gamma treatment for ovarian cancer caused a reduction of the proliferation-promoting TFs E2F1 and E2F2, at the same time it also increased the inhibiting TFs E2F4 and E2F5." (PMID 20181230, 2010). "Understanding the tumor-promoting mechanisms and cellular and molecular targets of IFNγ in ovarian cancer is crucial for minimizing its tumor-promoting functions in PD-1/PD-L1-blocking cancer immunotherapies that induce IFNγ expression and in other therapies associated with IFNγ release." (PMID 39123403, 2024). "Interferon-gamma (IFN-γ), in particular, has been shown to induce PD-L1 expression in ovarian cancer cells, facilitating disease progression." (PMID 40002913, 2025). "In BRCA1-mutated ovarian cancers, the main functions identified were related to the immune system, such as MHC assembly, CD4 and CD25 regulation, and regulation of the interferon gamma pathway, among others." (PMID 40647506, 2025). "In vivo screening of interferon gamma (IFN-γ)-polarised M1 CAR-iMACS in an ovarian cancer model showed that CAR-iMACS has a rapid expansion rate and can persist for more than 20 days in a system with significant anticancer activity." (PMID 40574837, 2025). "This study also showed that CXCL9 protein secretion occurred from ovarian cancer cell lines after the addition of IFNG and TNFA using cell culture, which is substantiated by our findings that CXCL9 as well as AIM2 are target genes for IFNG." (PMID 40492347, 2025). "In another analysis of HGSOC subtypes, other subtypes with inferior tumor immune response show PD-L1 regulation and increased tumor growth in ovarian cancer via interferon-gamma, or significantly reduced cytotoxic activity and T cell-related gene expression." (PMID 40002574, 2025). "Interferon gamma (IFN-γ) response in ovarian cancer is a topic of interest due to its potential role in the tumor microenvironment and immune modulation." (PMID 40953111, 2025). "In ovarian cancer cells, interferon-gamma (IFN-γ) promotes an increase in PD-L1 expression, which aids disease progression." (PMID 40805123, 2025). "Blocking IL-8 expression with IL-8-neutralizing antibodies also suppressed the invasion of IFNγ-stimulated ovarian cancer cells grown in 3D spheroids." (PMID 39123403, 2024).
ovarian carcinoma (continued). "In this review, we summarize the recent findings on the IFNγ tumor-promoting functions and on the mechanisms by which IFNγ induces Bcl3, PD-L1 and IL-8 expression in cancer cells, with a special focus on ovarian cancer." (PMID 39123403, 2024). "Since both PD-L1 and IL-8 induce proliferation, migration and invasion in OC cells, their IFNγ-induced expression likely contributes to the tumor-promoting effects of IFNγ in ovarian cancer." (PMID 39123403, 2024). "Recent studies have shown that IFNγ induces the expression of Bcl3, which then promotes the expression of PD-L1 and IL-8 in ovarian cancer cells, resulting in their increased proliferation and migration." (PMID 39123403, 2024). "In this review, we summarize the recent findings on how IFNγ affects the tumor microenvironment and promotes tumor progression, with a special focus on ovarian cancer and on Bcl3, PD-L1 and IL-8/CXCL8 signaling." (PMID 39123403, 2024). "In ovarian cancer cells, the tumor-promoting effects of IFNγ are mediated by increased expression of the proto-oncogene Bcl3, the immune checkpoint PD-L1 and the proinflammatory cytokine IL-8." (PMID 39123403, 2024). "DNMT inhibitors (DNMTi) have shown promising results in ovarian cancer in preclinical models by enhancing IFNγ-mediated and type-I interferon-mediated inflammatory responses." (PMID 37894317, 2023). "Prior studies have provided evidence that interferon-gamma (IFN-γ) triggers an elevation in PD-L1 expression in ovarian cancer cells, contributing to disease progression." (PMID 37894913, 2023). "Increased IFNγ and TNFα production by CD8 T cells and NK cells was also observed in a BRCA1-deficient ovarian cancer model upon treatment with PARPis." (PMID 36831435, 2023). "For example, IFNγ therapeutic utility has been investigated in patients with ovarian cancer: intraperitoneal IFNγ administration resulted in activation of tumour cytotoxicity and clinical responses." (PMID 36439180, 2022). "Currently, although numerous molecular subtyping has been developed in ovarian cancer, such as IFNG, CD30, CXCL13, PRF1 GBP1, and ETV7 CTLA-4, they provided limited prognostic information or are not validated in the clinical samples." (PMID 36157232, 2022). "When compared to controls, the CAM1615HER2 TriKE also showed increased CD107a and IFNγ NK cell activity against a broad panel of ovarian cancer cell lines including OVCAR3, OVCAR5, OVCAR8, and OVCAR4 cell lines." (PMID 34439149, 2021). "As a result, ovarian cancer cell lines Ovsaho and Kuramochi, pre-treated with DNMTi, induced increased release of IFNγ in TICS." (PMID 32200422, 2020). "In order to address this, in vitro activation of human NK cells with IL-12, IL-15, and IL-18 has been found to result in enhanced IFNγ production with effective killing of cancer cells in vitro as well as in an in vivo mouse model of ovarian cancer." (PMID 32937961, 2020). "For example, in ovarian cancer and angiosarcoma, IFNγ induces PD-L1 expression and is known to be involved in immune tolerance." (PMID 31914969, 2020). "Specifically, immunomodulators and interferon gamma have been proposed as a therapeutic target in ovarian cancer." (PMID 33519907, 2020). "Of note, the cam1615B7H3 TriKE induced similar degranulation and stronger IFNγ production against ovarian cancer when compared to a potent natural cytotoxicity signal, in the absence of TriKE, induced by K562 cells." (PMID 32961861, 2020). "All ovarian cancer cell lines tested demonstrated a significant induction of PD-L1 by interferon gamma, which was further increased by epigenetic therapy that activated type I interferon signaling." (PMID 32103105, 2020). "In contrast to cytolytic capacity, the production and release of IFNγ out of NK cells were suppressed in the presence of anti-EGFR TKI-sensitized ovarian cancer cells." (PMID 31546690, 2019). "For example, CD44 expression can be decreased by interferon gamma (IFNg) in ovarian carcinoma cells." (PMID 31856847, 2019).
ovarian carcinoma (continued). "Background activation of unmodified control NK-92 cells was highest against primary ovarian cancer cells (P2) leading to only a 16-fold increase of IFNγ expression." (PMID 30717444, 2019). "The detection of IFNγ-positive NK cells by flow cytometry in the presence of erlotinib-sensitized ovarian cancer cells and cetuximab was reduced significantly." (PMID 31546690, 2019). "Confirming this data, the frequency of IFNγ-positive NK cells in the ELISpot after co-incubation with sensitized ovarian cancer cells was also diminished significantly." (PMID 31546690, 2019). "We determined the production and secretion of IFNγ of NK cells in the presence of cetuximab and sensitized ovarian cancer cells." (PMID 31546690, 2019). "Specifically, Tregs inhibit the proliferation of CD8+ T cells as well as their production of IFNγ and IL-2, counteract the protective effect of cytotoxic T cells in ovarian cancer tissues, thus reversely correlated with patient survival." (PMID 28929459, 2018). "We demonstrate the feasibility of performing drug-screening by using ovarian cancer cells treated with interferon gamma (IFNγ)." (PMID 29242379, 2018). "For example, while IFNγ appears to be effective in treating adult T cell leukemia and ovarian cancers, it is relatively ineffective for most patients suffering from chronic myeloid leukemia." (PMID 29855346, 2018). "In keeping with these observations, elevated IFNG expression in ovarian cancer tumor tissue correlated with an improved clinical outcome in patients." (PMID 28327095, 2017). "Accordingly, the application of an anti-CCR4 antibody in an experimental model of ovarian carcinoma blocked Treg migration and enhanced antitumor response including increased IFNγ secretion by CD8+ T cells." (PMID 28275576, 2017). "Expression of this IFN-related signature also showed a striking link to a longer survival, and IFNγ abrogated the inhibitory effect of ovarian cancer ascites on the inducibility of IL-12 in cultured macrophages." (PMID 28327095, 2017). "For example, Low-dose decitabine treatment recruit NK and CD8+ T cells, promotes their production of IFNγ and TNFα, and extends the survival of ovarian cancer." (PMID 27435207, 2016). "An increase in the Tr1 cell : FoxP3+ tTreg ratio was associated with longer survival in a small clinical study of four recurrent ovarian cancer patients undergoing adoptive T cell transfer with autologous IL-10 and interferon gamma (IFN-γ)-producing Teff." (PMID 27509527, 2016). "Release of multiple inflammatory cytokines into the plasma, including IFNγ, IL-1β, IL-6, IL-8, IL-10, TNFα, PlGF, and HSP90B1, is frequently associated with epithelial ovarian cancers (EOC)." (PMID 26858849, 2015). "Administration of the classical M1 macrophage activator IFNγ had beneficial effects in patients with ovarian carcinoma." (PMID 25228902, 2014). "Ovarian cancer requires angiogenesis to grow, so the antiangiogenic effects of IFNγ are one possible therapeutic mechanism." (PMID 21674047, 2011). "Themis2 mRNA expression is also reported to be regulated by IFNγ or estrogen treatment of ovarian cancer cell lines." (PMID 20644716, 2010). "In ovarian carcinoma cells, the combination of interferon-gamma (IFN-gamma) and cisplatin (cDDP) has been reported to result in a synergistic amplification of antiproliferative activity." (PMID 9374379, 1997). "In addition, high levels of released GrB and IFNγ were observed in all primary ovarian cancer cells co-cultured with αPD-L1-γδ T cells." (PMID 40842867, 2025). "While early studies suggested that increased IFNγ levels correlate with improved clinical outcomes in patients with ovarian cancer, more recent studies have shown that high IFNγ expression in OC tissues promotes cancer progression and correlates with poor survival." (PMID 39123403, 2024).
ovarian carcinoma (continued). "In ovarian cancer (OC) cells, the tumor-promoting functions of IFNγ are mediated by IFNγ-induced expression of Bcl3, PD-L1 and IL-8/CXCL8, which have long been known to have critical cellular functions as a proto-oncogene, an immune checkpoint ligand and a chemoattractant, respectively." (PMID 39123403, 2024). "Since Bcl3, PD-L1 and IL-8 promote tumorigenesis, combinatorial strategies targeting the IFNγ-induced Bcl3, PD-L1 and IL-8 expression in ovarian cancer may enhance the antitumor effects of cancer immunotherapies." (PMID 39123403, 2024). "In humans, an IFNG-associated type 1 immune signature is associated with improved prognosis in human CRC patients, and similarly predicts prolonged patient survival across multiple other cancer types such as breast, liver, and ovarian cancers." (PMID 37455828, 2023). "The IFNγ‐induced Bcl3 promotes expression of interleukin‐8 (IL‐8) in ovarian cancer cells." (PMID 37151134, 2023). "Notably, the PARP1 inhibitor talazoparib (BMN 673) elicited increased numbers of peritoneal CD8+ T cells and NK cells in an ovarian cancer mouse model and increased infiltration into ex vivo spheroids, in addition to increasing IFNγ and TNFα production levels." (PMID 37752135, 2023). "We have recently shown that IFNγ, produced during cancer therapy, induces expression of the Bcl3 proto‐oncogene in ovarian cancer (OC) cells, resulting in their increased proliferation, migration, and invasion, but the mechanisms are unknown." (PMID 37151134, 2023). "Recent findings demonstrate that Cyst(e)inase treatment in combination with anti-PD-L1 checkpoint blockade synergistically enhanced T cell-mediated anti-tumor immunity, elevating tumoral lipid ROS and increasing populations of IFNγ/TNF expressing CD8 + /CD4 + T cells in an ovarian cancer model." (PMID 37170264, 2023). "Performing ELISpot assay we could observe that secretion of IFNγ of NK cells cocultured to ovarian cancer cells was substantially reduced in presence of malignant ascites while benign ascites did not affect secretory NK cell function." (PMID 37684704, 2023). "Furthermore, RNA-seq analyses of unmatched ovarian cancer primary ovarian tumors and primary malignant ascites revealed an IFNγ-stimulated inflammatory macrophage signature shared across ascites samples but not in solid tumor samples." (PMID 36860657, 2023). "Combination therapy induces immune activation probably in a STING-independent manner, including increasing the expression of IFNγ and related immunostimulatory chemokines, enhancing the systemic production of TNFα and IFNγ, and increasing the number of TILs in patients with ovarian cancer." (PMID 34712221, 2021). "In murine models of human ovarian carcinoma or murine sarcoma, SM administration was associated with a rapid inflammatory burst of TNF and interferon-gamma (IFNγ), due to the reversion of tumour-associated macrophages from a pro-tumoural M2 phenotype to a pro-inflammatory MI-like phenotype." (PMID 31947615, 2020). "We hypothesize that autologous monocytes stimulated with IFNα and IFNγ will prime an immune response to control the intraperitoneal growth of ovarian cancer." (PMID 30871636, 2019). "In addition, as seen in ovarian cancer, there was also a clear link between the expression of IFNG, CXCL13, CD30, and PRF1 and presence of immune cells within the tumor, including B cells, CD8+ T cells, CD4+ T cells, dendritic cells, and neutrophils." (PMID 31998644, 2019). "Moreover, in previous studies, IFNγ has the potential to be used clinically in the treatment of malignant glioma, ovarian cancer, and as a promising adjunct to be used to other immunotherapeutic modalities." (PMID 30782607, 2019). "Thus, as a proof of concept we interrogated alterations induced by IFNγ on the UWB.1 289 ovarian cancer cell line." (PMID 29242379, 2018).
ovarian carcinoma (continued). "Furthermore, we also demonstrated the feasibility of performing comparative screening using an ovarian cancer cell line treated with the pro-inflammatory cytokine IFNγ." (PMID 29242379, 2018). "Furthermore, IFNγ inclusion in the first-line therapy of ovarian cancer resulted in an effector immune cell response and a prolongation of progression-free survival, while type I IFNs had no benefit." (PMID 28327095, 2017). "Multiple observations strongly support the hypothesis that IL-12, and probably its induction by IFNγ, are crucial determinants of ovarian cancer outcome." (PMID 28327095, 2017). "Therefore, it was conceivable that both CD3+ T cell subpopulations, Th1 cells and CTLs, contribute to the antitumor response in ovarian carcinoma by maintaining IFNγ production." (PMID 28275576, 2017). "Neutralization of IFNγ-induced IL-8 using an anti-IL-8 blocking antibody reduces IFNγ-induced migration of OC cells and their invasion ability in 3D spheroids, indicating that IFNγ-induced IL-8 expression contributes to the pro-tumorigenic effects of IFNγ in ovarian cancer cells." (PMID 39123403, 2024). "In mouse ID8 ovarian cancer metastasis, the depletion of autophagy related gene FIP200 in peritoneal TAMs induced T cell mediated anti-tumor response which may be due to the spontaneous IFNγ mediated immune activation in autophagy deficient TAMs." (PMID 36035994, 2022). "Mechanistically, activated CD8+ T cells could release interferon-gamma (IFN-γ), which inhibited cystine uptake by downregulating the expression of system Xc-, as a result, promoting lipid peroxidation accumulation and ferroptosis in ovarian cancer cells." (PMID 36438923, 2022). "Additionally, it has recently been identified that the critical soluble mediators of type-1 immune effector cells, IFNγ and TNFα, synergize in the induction of COX-2, the key enzyme in PGE2 synthesis, implicated in hyperactivation of MDSC within the TME of ovarian cancer patients." (PMID 28536377, 2016). "pGSN in exosomes also induced CD8(+) T-cell apoptosis, leading to reduced IFNγ secretion and increased glutathione (GSH) production in ovarian cancer cells, enhancing resistance to CDDP-induced cell death." (PMID 39334866, 2024). "We found that XBP1 was significantly correlated with key immunity-killing molecules, including FASL, PRF1, IFNG, GZMB, TNFa, and CD40L in ovarian cancer." (PMID 35991556, 2022). "Ovarian cancer cells are capable of expressing MHC-II related genes, often in response to inflammatory signaling processes induced by high levels of IFNγ in the TME." (PMID 32937961, 2020). "We found that the combined expression of IFNG, CD30, CXCL13, and PRF1 correlated with better overall survival (OS) in advanced stage ovarian cancer." (PMID 31998644, 2019). "Western blot analysis results showed that interferon gamma treated ALST and OVCA5 ovarian cancer cells had a significant decrease in phosphorylated ERK and P38MAPK protein levels when compared to control solvent treated cells." (PMID 30469497, 2018). "For instance, an anti-CCR4 antibody mAb2-3 blocks Treg migration and stimulates IFNγ secretion by CD8+ T cells, eventually enhancing anticancer response in an experimental model bearing CCL22-secreting ovarian cancer cells." (PMID 28929459, 2018). "Furthermore, IFNγ counteracted repression by ovarian cancer ascites of IL-12, a key mediator of an anti-tumor response mediated by natural killer cells (NK) and T lymphocytes, consistent with the observed association of an IFN signaling-associated signature with ovarian cancer survival." (PMID 28327095, 2017). "In this study we found that TNFα, IFNγ and MUC16 are often strongly co-expressed in endometrial, breast and ovarian cancers with cytokine staining intensity positively correlating with MUC16 staining in breast and ovarian cancers, in particular." (PMID 26918940, 2016).